ENSG00000278526
Gene: Miscellaneous RNA gene on chromosome 7 (117,190,133 to 117,190,269, forward strand). Ensembl gene ENSG00000278526.
Homologues: Orthologues: mouse Gm55218 (99% identical).